RN7SKP40 (RN7SK pseudogene 40)
Gene: Miscellaneous RNA gene on chromosome 3 (174,631,823 to 174,632,064, forward strand). Ensembl gene ENSG00000253020.
Homologues: Orthologues: chimpanzee 7SK (100% identical), mouse Gm54807 (50% identical). Paralogues in human: RN7SKP224 (68% identical), RN7SKP192 (66% identical), RN7SKP217 (66% identical), RN7SKP282 (66% identical), RN7SKP77 (66% identical), RN7SKP133 (65% identical), RN7SKP230 (65% identical), RN7SKP250 (65% identical), RN7SKP50 (65% identical), RN7SKP87 (65% identical), RN7SKP184 (65% identical), RN7SKP8 (65% identical), and 284 more.